CDX2 (caudal type homeobox 2)
Diseases named in the same sentence as CDX2 in open-access papers (continued):
Sharing a sentence is not in itself a finding about the gene and the disease.
sarcopenia (1 paper, 2018). Progressive decline in muscle mass due to aging which results in decreased functional capacity of muscles. "From genetic point of view, we showed a putative association among polymorphisms FokI and Cdx2 of VDR gene, vitamin d receptor activation and the occurrence of sarcopenia." (PMID 30574409, 2018).
sinonasal carcinoma (1 paper, 2025). "Expression of CDX2 and hepatocyte-specific antigen has been reported in the SMARCB1-deficient sinonasal carcinoma previously." (PMID 40366517, 2025). "Caution should be exercised when interpreting the expression of lineage-specific markers, such as TTF1 and CDX2, in poorly differentiated sinonasal carcinomas to avoid misclassification." (PMID 40366517, 2025).
sinonasal undifferentiated carcinoma (1 paper, 2017). A rare, highly aggressive carcinoma that arises from the sinonasal tract. "While CDX-2 is helpful when diagnosing ITAC, it is not fully specific as it can sometimes be expressed in sinonasal undifferentiated carcinomas and in salivary-type sinonasal adenocarcinomas." (PMID 28321774, 2017).
small intestinal cancers (1 paper, 2020). "Taking these evidences into consideration, it is difficult to completely distinguish between colon and small intestinal cancers solely by the expression statuses of CDX2 and/or SATB2." (PMID 32867793, 2020).
Thrombocytopenia (1 paper, 2020). A reduction in the number of circulating thrombocytes. "Scl:Cdx2/Flt3ITD/+ double mutants showed severe thrombocytopenia and succumbed to advanced MPN characterized by splenomegaly and increased in Gr1−positive myeloid cells in PB compared with control or single knockin Cdx2 mice." (PMID 32541670, 2020). "Approximately 20% of Scl:Cdx2 mice did not develop overt hematological disease aside from thrombocytopenia and neutrophil dysplasia." (PMID 32541670, 2020). "All moribund mice had reduced hemoglobin compared with controls while all Scl:Cdx2 mice (regardless of health state) showed mild to profound thrombocytopenia." (PMID 32541670, 2020).
tuberculosis (1 paper, 2022). A chronic, recurrent infection caused by the bacterium Mycobacterium tuberculosis. "CdX-2 AA is associated with an increased risk for tuberculosis and overall risk for cancer." (PMID 36490235, 2022).
ulcer (1 paper, 2012). "The down-regulation of cdx-2 mechanism was related to the induction of ulcer-associated cell lineage (UACL)." (PMID 22824143, 2012).
ulcerative colitis (1 paper, 2025). An inflammatory bowel disease involving the mucosal surface of the large intestine and rectum. "The expression of CDX2 is decreased in ulcerative colitis, and the absence of CDX2 in intestinal epithelial cells also leads to macrophage infiltration, which results in chronic inflammation." (PMID 40076032, 2025).
upper respiratory tract infection (1 paper, 2023). "A recent cohort study conducted in a mixed population (725 subjects) showed a significant association between the Cdx2 (rs11568820-AA) genotype and the susceptibility to upper respiratory tract infection (p = 0.001; OR = 1.31; 95% CI = 1.12–1.53; AA vs. GG)." (PMID 36839181, 2023).
urethral tumor (1 paper, 2014). "The present case exactly showed the phenotype of CK20+/CK7-/CDX2+, suggesting that the urethral tumor was derived from primary tumor of sigmoid colon." (PMID 24884559, 2014). "Moreover, immunohistochemistry of the urethral tumor showed the positive for cytokertin (CK) 20 and CDX2, the intestinal epithelia-specific nuclear transcription factor, whereas negative for CK7." (PMID 24884559, 2014).
viral infection (1 paper, 2025). "Confocal microscopy was employed to visualize caudal type homeobox 2 (CDX2)-GFP labeling, marking intestinal identity in green, and red fluorescence corresponding to immunofluorescence staining of filoviral nucleoprotein (NP) or nucleocapsid (NC), which confirmed viral infection." (PMID 41284734, 2025).
vitamin D deficiency (1 paper, 2016). A nutritional condition produced by a deficiency of VITAMIN D in the diet, insufficient production of vitamin D in the skin, inadequate absorption of vitamin D from the diet, or abnormal conversion of vitamin D to its bioactive metabolites. "In this study, we will evaluate whether vitamin D deficiency and Cdx-2, FokI, BsmI and TaqI polymorphisms of the VDR gene are associated with POAG in the Han population of China." (PMID 27435453, 2016).
Wilms tumor (1 paper, 2014). An embryonal neoplasm characterized by the presence of epithelial, mesenchymal, and blastema components. "In the context of a single gene giving rise to alternatively spliced transcripts that produce proteins regulating transcription or splicing, CDX2 shares considerable similarity with the Wilms’ tumor gene, WT1." (PMID 25101906, 2014).
tumor (454 papers, 2001 to 2026). "We observed a statistically significant association between MMR deficiency and younger age at diagnosis, female sex, right-sided tumor location, poor tumor differentiation, and loss of CDX2 expression." (PMID 40941629, 2025). "Low CDX2 expression is linked to aggressive pathological features and advanced tumor stage in CRC, highlighting its clinicopathological associations." (PMID 41388313, 2025). "It was significantly associated with younger age (<50 years), female sex, right-sided tumor location, poor tumor differentiation (G3), smoking, and loss of CDX2 expression (p < 0.001)." (PMID 40941629, 2025). "Previously, only a few studies have examined the associations between tumor-infiltrating immune cells and the expression of CDX2 or SATB2 in CRC." (PMID 39998677, 2025). "CDX2 loss is often seen in cases of chromosomal instability and is expressed in a more heterogeneous manner throughout the tumor tissue." (PMID 40619482, 2025). "Our findings show that poor differentiation and advanced local tumor stage are highly associated with reduced CDX2 expression, despite the fact that it is rather uncommon (11.2%)." (PMID 41388313, 2025). "These tumours also express tumour‐associated genetic markers (e.g., CD44v6, CDX2, BRAF) and immune markers (e.g., CD68, CD163), alongside characteristics like CpG island methylator phenotype and KRAS mutations." (PMID 40444502, 2025). "CDX2 is a gene encoding transcription factors involved in intestinal oncogenesis, and its reduced expression has been linked to more aggressive tumor behavior." (PMID 40142201, 2025). "Low-CDX2-expression tumours were also associated with lower rates of disease-free survival (p = 0.009), cancer-specific survival (p < 0.001) and recurrence-free survival (p = 0.004)." (PMID 39201360, 2024). "Loss of CDX2 expression was detected in 27 (7.8%) samples, enriched in poorly differentiated tumours (20%; p < 0.01) and in those with the BRAF p.V600E variant (40%; p < 0.01)." (PMID 38439814, 2024). "The Fisher’s Exact test revealed a statistically significant association between the CDX2 immunohistochemical expression categories and the tumor budding score (p = 0.002)." (PMID 38786321, 2024). "Cdx2-mediated proximal colon-specific transcriptional program concurrently is tumor suppressive, and Cdx2 loss sufficiently creates permissive state for BRAFV600E-driven transformation." (PMID 38360902, 2024). "The rate of CDX2 loss was significantly increased in right-sided primary tumours when compared to CDX2-expressing tumours from two studies." (PMID 38439814, 2024). "This study found that tumours with low CDX2 expression were associated with more aggressive features of cancer and worse outcomes for patients." (PMID 39201360, 2024). "Loss of CDX2 expression in mCRC was associated with higher risk of patient death and progression after first-line treatment, poorly differentiated tumours and the BRAF p.V600E variant." (PMID 38439814, 2024). "The loss of CDX2 expression in mCRC was associated with a higher risk of death and progression after first-line treatment, and with poorly differentiated tumours, and the somatic BRAF p.V600E variant." (PMID 38439814, 2024). "Inconsistent with our findings, several studies showed that CDX2 expression was significantly associated with sex, vascular invasion, and tumor stage." (PMID 37602699, 2023). "Although clinicopathological features such as advanced tumor stage, vascular invasion, and poor differentiation have also been suggested to be associated with loss of CDX2, the association has been inconsistent between studies." (PMID 37962682, 2023). "This is supported by publications describing that overexpression of CDX2 in tumor cells deficient in CDX2 exerts tumor suppressor activity by inducing intestinal differentiation, reducing cell proliferation, and reversing epithelial‐to‐mesenchymal transition." (PMID 37602699, 2023).
tumor (continued). "PD-L1 expression in ≥1% of tumor cells was associated with CDX2 negativity, right-sided cancer, dMMR, and a high infiltration of CD3+ and CD8+ intraepithelial and stromal TILs." (PMID 36110945, 2022). "CDX1 (together with CDX2) can function as a tumor suppressor and concomitant loss of CDX1 can significantly increase the incidence of tumors APC(Min/ +)-Cdx2 mice." (PMID 35715570, 2022). "In tumour cells, expression of HLA-G and loss of CDX2 expression were associated with cancer recurrence." (PMID 35027037, 2022). "We show that there is a large overlap between dMMR and the loss of CDX2 expression and between dMMR and a high tumor grade." (PMID 36110945, 2022). "Although tumor bud count, stroma type, and the CDX2 expression status in tumor buds were identified as risk factors for LNM, only tumor bud count was significantly correlated with local recurrence in patients with pT1 CRC." (PMID 36186777, 2022). "The loss of CDX2 expression and low tumor grade in isolation are regarded as poor prognostic features." (PMID 36110945, 2022). "Based on the univariate logistic regression analysis results of the training cohort, seven factors, namely general tumor type, histology grade, LVI, tumor bud stroma, tumor bud count, tumor bud cell mitosis, and CDX2 expression, were linked to the LNM status." (PMID 36186777, 2022). "For example, ~30% of human CRC exhibits loss of Cdx2, and this is associated with higher tumor grade." (PMID 33525395, 2021). "Generally confirming previous data, we observed significantly shorter survival parameters for CRC patients whose tumours showed a CDX2 loss in univariate analyses in our first general screening of the overall cohort." (PMID 34616012, 2021). "CDX-2 is downregulated in the invasive part of tumor tissues and is associated with tumor-stroma protein expression as well as inflammatory cytokine release in CRC." (PMID 33632198, 2021). "In recent years, it was found that CDX2 suppression is associated with tumor invasion and migration, and the underlying mechanism involves promoting cell junction protein expression and inhibiting EMT." (PMID 33621200, 2021). "Although both expression groups were associated with one another (p < 0.001), there were many tumours with a discordant SATB2/CDX2 expression status (Kappa Cohens value: 0.30)." (PMID 34944797, 2021). "For patients given first-line combination chemotherapy with response registered (n = 194 of 217), objective response rate was 35% if the tumor showed CDX2 loss and 49% if CDX2 was expressed." (PMID 32117703, 2020). "Cdx1 and Cdx2, two of the three mammalian orthologues of pal-1/caudal, have been implicated in the formation of epithelial-derived tumours." (PMID 31923384, 2020). "Median OS in the whole cohort (untreated and treated with chemotherapy) was 6 months if tumor had CDX2 loss and 13 months if tumor showed CDX2 expression (p < 0.001)." (PMID 32117703, 2020). "CDX2 loss was associated with right-sided primary tumor, poor differentiation, MSI-H, BRAFmut, and KRAS wild type (KRASwt)." (PMID 32117703, 2020). "In patients with double (KRAS and BRAF) wild-type tumor, median OS was 10 months if CDX2 loss (n = 10) compared to 27 months if CDX2 expressed (n = 77) (p = 0.576)." (PMID 32117703, 2020). "The aim of this study was to determine the prevalence, prognostic, and predictive effect of CDX2 loss in unselected patients of mCRC in relation to tumor differentiation, BRAF, KRAS, and MSI status." (PMID 32117703, 2020). "Patients with KRASmut tumor had median OS of 11 months if CDX2 loss (n = 4) compared to 21 months if CDX2 expressed (n = 83) (p = 0.007)." (PMID 32117703, 2020). "When the Apc∆716 mutant allele is combined with the Cdx2+/− heterozygous mutation, there is a large increase in the number of adenomatous polyps in the distal colon, more closely reflecting the tumor distribution in human FAP." (PMID 31739541, 2019).
tumor (continued). "Caudal-related homeobox transcription factor (CDX2) is an intestinal transcription factor whose loss is associated with high tumor grade, advanced stage in CRC, and poor prognosis in GC." (PMID 31179189, 2019). "On the same line CDX2 immunohistochemistry was conducted on the diagnostic cytological specimens to confirm the digestive source (and namely pancreatic) origin of tumor cells." (PMID 31249555, 2019). "The combination of CK7+/CDX2+ immunostaining and the distinctive genetic signatures, including low incidence of sensitivity genes mutations and high tumor mutation burden, is an important supplementary to the clinical differential diagnosis of primary PEACs." (PMID 29587865, 2018). "We noticed that tumours with positive or moderate CDX2 expression in general, showing focal loss of CDX2 expression in the budding cells in particular, reflected a surprisingly poor prognosis." (PMID 30425348, 2018). "Significant relationships between loss of CDX2 expression and high malignancy grade, right-sided tumours, and dMMR were validated (p < 0.0001)." (PMID 30425348, 2018). "Low LRP1 immunohistochemical expression in adenocarcinomas was associated with higher age, right-sided tumor, loss of CDX2 expression, Annexin A10 expression, CIMP-H, MSI-H and BRAFV600E mutation." (PMID 29507659, 2018). "CDX2 is involved in the intestinal cell differentiation in normal cells, and low CDX2 in tumor tissue is associated with a poorer cancer-specific survival." (PMID 30038723, 2018). "More than 20% of CRCs show some degree (or complete loss) of CDX2 protein in the tumor, which is often reported along with a preponderance for female gender and right-sided tumor location, two features frequently associated with serrated lesions." (PMID 30257705, 2018). "Loss of CDX2 expression in the budding cells was more frequently encountered in pMMR tumours 69/815 = 8% compared to microsatelite instable tumours 11/342 = 3%, p = 0.0013." (PMID 30425348, 2018). "CDX2− carcinomas were associated with reduced 3‐year (60 per cent versus 77·8 per cent for CDX+ tumours; P = 0·018) and 5‐year (51·0 versus 70·1 per cent respectively; P = 0·009) overall survival." (PMID 30511046, 2018). "Especially the subgroup with focal CDX2 loss of budding tumour cells in the CDX2-moderate group actually fared even worse than the CDX2-negative group with a 5-year DFS as low as 60%." (PMID 30425348, 2018). "Caudal‐related homeobox transcription factor 2 (CDX2) is an intestine‐specific transcription factor implicated in tumour differentiation, proliferation, cell adhesion and migration." (PMID 30511046, 2018). "We present a novel mouse tumor model based on signature defects seen in many human serrated CRCs – CDX2 loss and BRAFV600E." (PMID 28072391, 2017). "Our findings are in line with previous work from our group using a single punch tissue microarray showing strong correlations between Cdx2 loss and pT, pN, tumor grade, and vascular invasion on more than 1000 tumors." (PMID 24130965, 2013). "All these studies confirm that expression of cdx-2 gene though disease specific and tissue specific, the expression of cdx2 was directly associated with tumor growth." (PMID 22824143, 2012). "CDX-2 is a mammalian homeobox gene, encoding a nuclear transcription factor, which is implicated as a tumor suppressor." (PMID 23121893, 2012). "While CDX2 mutations predisposing to sporadic CRC have not been identified, this study has established that loss of CDX2 contributes towards the progression of some sporadic CRC tumours." (PMID 11161380, 2001). "There may be an inverse relationship between CDX2 levels and tumor stage, as loss of CDX2 expression has been shown in a number of CRC cell lines." (PMID 41373479, 2025).